CTLA4 (cytotoxic T-lymphocyte associated protein 4)
Diseases named in the same sentence as CTLA4 in open-access papers (continued):
Sharing a sentence is not in itself a finding about the gene and the disease.
melanoma (continued). "Collectively, these results suggest that the four-gene TIR signature is a predictor of anti-CTLA4 immunotherapy response and survival of melanoma patients." (PMID 33753855, 2021). "Targeting of blocking programmed cell death protein (PD-1) and cytotoxic t-lymphocytes antigen 4 (CTLA-4) have prolonged malignant melanoma relapse-free, distant metastasis-free, and overall survival times." (PMID 34831094, 2021). "CTLA-4 is also a direct target gene of Wnt/β-Catenin in melanoma: it increases the production of IFN-γ by CD8+ and CD4+ TILs." (PMID 34830209, 2021). "Several ICI drugs targeting CTLA-4 or PD-1/PD-L1 interaction have been approved by the FDA for various cancer types including melanoma, lung cancer, renal cell carcinoma, breast cancer, head and neck cancer, colorectal cancer, urothelial cancer and HCC 18-33." (PMID 34104078, 2021). "Preclinically, we demonstrated that combination treatment of Sunitinib and CTLA4 mAb significantly alleviated tumor burden and OS in melanoma and NSCLC immune competent mouse models." (PMID 33510997, 2021). "Two monoclonal CTLA-4 antibodies have been developed and undergone clinical testing; Ipilimumab has been effective in the treatment of melanoma, and Tremelimumab has been used in multiple phase III clinical trials." (PMID 34239985, 2021). "EZH2 inhibition together with anti-CTLA-4 has combinatory effects in melanoma and bladder cancer models." (PMID 33859645, 2021). "MAP2K1/2 mutations were identified as an independent predictive factor for anti-CTLA-4 therapy in melanoma patients." (PMID 35069558, 2021). "Immune checkpoint blocking antibodies, including anti-CTLA-4 and anti-PD-1, can induce tumor responses in a variety of tumor types, including melanoma, non-small-cell lung cancer (NSCLC), and kidney renal clear cell carcinoma (KIRC)." (PMID 34194607, 2021). "Since the anti‐CTLA‐4 ICI Ipilimumab was approved for the treatment of melanoma in 2011, the number of ICI and ICI treatment approved tumor entities has steadily risen." (PMID 33449393, 2021). "Patients with high tumor CTLA-4 expression in mesothelioma, nasopharyngeal carcinoma and melanoma had a poorer prognosis than those with low expression, which suggested CTLA-4 as a potential target for tumor immunotherapy." (PMID 33906311, 2021). "For example, a recent phase-II clinical trial proved that the combination of ipilimumab (a CTLA-4 inhibitor) and nivolumab (a PD-1 inhibitor) significantly improved treatment efficacy in advanced melanoma patients compared with monotherapy with ipilimumab." (PMID 34876903, 2021). "Inhibiting CTLA-4 and PD-1/PD-L1, leading to enhanced immune system activation, has contributed to the development of novel melanoma immunotherapies." (PMID 34804979, 2021). "High C3 expression was associated with a good outcome of ICB therapy of PD1, CTLA4, and ACT in melanoma but was associated with worse PD and PDL1 outcomes in GBM and bladder cancer, respectively." (PMID 34439277, 2021). "Melanoma cells with Casp8 knocked down exhibited sensitivity to anti‐PD‐1 or anti‐CTLA‐4 antibody treatments, particularly in Ncr1iCre/+Casp8fl/fl mice." (PMID 33934451, 2021). "Pre-, during, and post-treatment stool samples were collected from 27 patients with advanced stage melanoma treated with IPI (anti-CTLA-4) and NIVO (anti-PD1) ICB inhibitors at NYU Langone Health." (PMID 34641962, 2021). "In contrast, high C5 expression was associated with a worse outcome of ICB therapy of PD1, CTLA4, and ACT in melanoma but predicted a good outcome of PD1 therapy in GBM and kidney cancer." (PMID 34439277, 2021). "For example, local chemotherapy combined with systemic checkpoint blocking inhibitor (CTLA-4 blockade) has been shown to improve the prognosis of patients with melanoma." (PMID 34513670, 2021). "At present, the commonly used ICIs for melanoma are pembrolizumab and nivolumab for PD-1 and ipilimumab for CTLA-4." (PMID 34877360, 2021).
melanoma (continued). "In the present study, we have successfully validated these findings in a homogeneous independent cohort of N = 30 melanoma patients treated with CTLA-4-targeted ICB (ipilimumab)." (PMID 33196890, 2021). "The efficacy and safety of combined cancer vaccine and ipilimumab were evaluated in one of the biggest phase III trials for CTLA-4 checkpoint blockade, which enrolled patients who had previously been treated for malignant melanoma." (PMID 34360800, 2021). "ICB is used to prevent T cell inactivation, and the most common antibodies used to treat melanoma patients include nivolumab and pembrolizumab, which prevent PD-1 from interacting with PD-L1, and ipilimumab, which blocks CTLA-4." (PMID 34944799, 2021). "Monotherapy with PD-1 antibodies or CTLA-4 antibodies individually have achieved somewhat lower rates of durable complete remissions in patients with melanoma." (PMID 34743688, 2021). "For instance, delivering GVAX in combination with anti-CTLA-4 antibody induced synergistic effects in controlling the tumor size and enhancing antitumor immune responses in melanoma and prostate cancer models." (PMID 34360800, 2021). "The combination therapy of axitinib with anti-CTLA-4 reduced tumor growth and increased survival in melanoma brain metastases models, both intracranial and subcutaneous." (PMID 32508809, 2020). "Checkpoint blockade with PD-1 and CTLA-4 showed durable control of highly aggressive melanomas and has led to spectacular results showing rapid eradication of large metastatic tumors in response to one dose of Ipilimumab (CTLA-4) and Nivolumab (PD-1)." (PMID 33262763, 2020). "With strong preclinical evidence of a robust antitumor immune response, C-REV progressed to a phase II clinical trial as a combination therapy with the CTLA-4 inhibitor ipilimumab for treatment of the late stages of unresectable melanoma (NCT02272855)." (PMID 33207653, 2020). "All four melanoma patients had previously failed treatment with both anti-PD-1 and anti-CTLA-4 monoclonal antibodies, at standard doses, either in monotherapy or in combination therapy." (PMID 33182610, 2020). "Due to the role that CTLA-4 and PD-1 play in the escape of cancer cells from immune system surveillance, they became targets in melanoma immunotherapy." (PMID 33171792, 2020). "On the other hand, data observed in melanoma patients treated with anti-CTLA-4 or anti-PD-1 therapy showed that the increase of sPD-L1 with a FC > 1.5, after 5 months of treatment, was associated with a favorable clinical outcome." (PMID 32033266, 2020). "Pneumonitis has been identified in less than 1% of patients treated with anti–CTLA-4 antibody, in 1–6% of those treated with anti–PD-1/anti–PD-L1 (1–2% for melanoma, 3–6% for lung cancer) and in 10% of patients during combined ICIs treatment." (PMID 32294888, 2020). "Ipilimumab is a fully humanized monoclonal anti-CTLA-4 antibody that was approved by the FDA in 2011 for the late-stage of melanoma." (PMID 32580338, 2020). "Approximately 30% patients with melanoma who had accepted the CTLA-4 blocking strategy developed to toxicity grades 3–4, suggesting that the inhibitor activated the systemic immune response rather than tumor-specific T cells." (PMID 33408716, 2020). "While multiple studies in melanoma brain metastases report intracranial objective responses with anti-PD-1 and/or anti-CTLA-4 immunotherapy, the evidence in NSCLSC BMs is limited to anti-PD-1 immunotherapy (i.e., predominantly nivolumab)." (PMID 32143288, 2020). "Immunotherapy has revolutionized cancer treatment, with ICIs including monoclonal anti‐PD‐1, anti‐PD‐L1, and anti‐CTLA‐4 having significantly improved survival outcomes in lung cancer and melanoma patients." (PMID 32833338, 2020). "Systemically delivered liposomal cGAMP along with anti-PD-1 and anti-CTLA4 treatment further shrunk the size of the pulmonary metastases of melanoma in mice, with persistent anti-tumor immunological memory." (PMID 32774773, 2020).
melanoma (continued). "In this trial, patients with melanoma must have had prior anti-PD-1/PD-L1 antibody (± anti-CTLA-4 antibodies or BRAF/MEK inhibitors) treatment and progressive disease." (PMID 32461587, 2020). "A gene signature related to memory B cells was reported to be associated with clinical benefit and improved survival in anti-PD-1- and anti-CTLA-4-treated melanoma patients and in anti-PD-L1-treated urothelial carcinoma." (PMID 32457745, 2020). "Ipilimumab, an anti-CTLA-4 mAb, shows a better effect on survival improvement in melanoma patients carrying the BRAF wild type compared to radiotherapy and chemotherapy." (PMID 32013263, 2020). "Various studies have addressed the relationship between overall tumor mutation load/neoantigen burden and ICB response in NSCLC and melanoma, in the context of anti-PD-1 and anti-CTLA-4 monotherapy." (PMID 31968651, 2020). "Specifically, high baseline levels of sPD-L1 were found to be negatively associated with clinical benefit in malignant melanoma and non-small cell lung cancer (NSCLC) patients treated with anti-CTLA-4 or anti-PD-1 mAbs, respectively." (PMID 32033266, 2020). "We have previously shown that the non-invasive neo-epitope biomarker PRO-C3 reflecting fibrotic activity and type III collagen deposition identifies melanoma patients with poor response to ICI therapy (anti-CTLA-4)." (PMID 32998446, 2020). "The authors found a significant association between the levels of these circulating miRNAs and reduced PFS and OS for melanoma patients treated with PD-1 and CTLA-4 inhibitors." (PMID 33036192, 2020). "Immune checkpoint blockade therapy that impedes the PD-1/PD-L1 and anti-CTLA-4 pathway can increase OS in patients with advanced melanoma, non-small-cell lung cancer, urothelial cancer, renal cell carcinoma and other cancer types." (PMID 33216727, 2020). "Recent clinical trials showed that blocking CTLA-4 and PD-1 simultaneously in patients with advanced melanoma strengthened the function of tumor-specific T cells, but resulted in off-target/on-target side effects." (PMID 32260561, 2020). "IT, particularly monoclonal antibodies targeting immune checkpoint pathways (PD-1/PD-L1 and CTLA-4), improves the OS of patients with advanced tumors, such as melanoma and NSCLC, which frequently develop BMs72." (PMID 33299643, 2020). "Combining telratolimod with both anti-CTLA-4 and anti-PD-L1 resulted in superior activity against treated and untreated tumours than single agents in B16.F10 melanomas, with both tumours displaying an increase in antigen-specific CD8+ T cells." (PMID 33352882, 2020). "A previous study found that the MHC proteins confer differential sensitivity to CTLA-4 and PD-1 blocking in melanoma." (PMID 33282564, 2020). "Additional evaluations are required to reveal a poor response to anti-PD-1/CTLA-4 therapy in patients with plasma cell-rich melanomas." (PMID 32582154, 2020). "Several subsets of effector CD4+ Th1 cells have been shown to be more abundant in melanoma tumors responding to CTLA-4 inhibition." (PMID 32457745, 2020). "Studies in mice conducted with intratumoural Pam3CSK4 combined with systemic administration of anti-CTLA-4 showed enhanced efficacy in a B16.F10 melanoma model." (PMID 33352882, 2020). "Ipilimumab was also able to trigger ADCC via the engagement of FcyRIIIA receptors present on primary NK cells as well as NK cells and γδT cells activated by IL-2 by reacting with CTLA-4 present on melanoma cell lines and tissues." (PMID 32117298, 2020). "This is consistent with ISV + α-CTLA-4 leading to T cell-dependent immune memory against melanoma brain metastases." (PMID 32690669, 2020). "Ipilimumab, as the first confirmed inhibitor for immune checkpoints that targets CTLA-4 molecules, has been applied for the treatment of those patients who suffer from advanced melanoma." (PMID 32340275, 2020). "In melanoma, these therapies target molecules that are pathologically overexpressed in melanoma such as PD-1 or CTLA-4." (PMID 32671117, 2020).
melanoma (continued). "In contrast, a previous study of malignant melanoma patients using a CTLA-4 inhibitor found that a lower baseline level of IL-6 was strongly associated with the development of irAEs, including colitis." (PMID 33317597, 2020). "For instance, the presence of bacteria from the Bacteroidetes phylum in stool samples of melanoma patients receiving anti-CTLA4 CPI, were less prone to treatment induced colitis." (PMID 33076303, 2020). "As targets of ICIs, higher expression levels of PD-L1 and CTLA-4 in melanoma often represent better clinical response and therapeutic efficacy." (PMID 33072607, 2020). "Nivolumab versus chemotherapy in patients with advanced melanoma who progressed after anti-CTLA-4 treatment (CheckMate 037): a randomised, controlled, open-label, phase 3 trial." (PMID 33268350, 2020). "This was a single institution, retrospective analysis of stage IV melanoma patients who received first-line anti-CTLA-4, anti-PD1, or combination anti-CTLA-4/anti-PD1." (PMID 32472413, 2020). "Administering monoclonal antibodies targeting the immune checkpoint PD-1, alone or in combination with anti-CTLA-4 blocking antibodies is, to date, the standard of care for advanced melanoma patients." (PMID 32858889, 2020). "Enrichment of clonal neoantigens in lesions enhanced the sensitivity of patients with NSCLC or melanoma to anti‐PD‐1 and anti‐CTLA‐4 therapy and promoted overall survival in patients with lung adenocarcinomas." (PMID 32997401, 2020). "We used flow cytometry to profile pretreatment tumor biopsies from 36 melanoma patients treated with anti-PD-1 or combination (anti-PD-1 plus anti-CTLA-4) immunotherapy." (PMID 33202676, 2020). "The widespread use of ICBT began in 2011 with the FDA approval of Ipilimumab, an anti-CTLA-4 treatment for advanced melanoma patients." (PMID 32380703, 2020). "The EMA, Japan and the Australian Therapeutic Goods Administration (TGA) approved ipilimumab (Yervoy), an immune checkpoint inhibitor of CTLA-4, for the treatment of melanoma." (PMID 33297561, 2020). "To assess the characteristics of AS neopeptides, we applied ASNEO to two published datasets of melanoma patients treated with CTLA4 inhibitors or PD-1 inhibitors." (PMID 32697765, 2020). "Here, we present evidence of a robust, long lasting, tumor-specific humoral immune response provoked by RT + IT-IC + anti-CTLA-4 in situ vaccination in a syngeneic murine melanoma model." (PMID 32849544, 2020). "In the clinic, Ariyan reported that the isolated limb infusion of melphalan with systemic ipilimumab, an CTLA-4 antibody, in patients with in transit melanoma, showed a durable increase in efficacy over ipilimumab alone." (PMID 32599852, 2020). "This is especially true for CTLA-4-targeting immunotherapy as the best response rates, found in melanoma patients, are about 20%." (PMID 31991588, 2020). "The source article of the melanoma transcriptome mainly discussed the role of the CNAs in modulating the response to CTLA-4 and PD-1 blockade." (PMID 33575206, 2020). "Increased frequency of a subset of NK cells (mature circulating CD3− CD56dim CD16+ NK cells) with increased TIM-3 expression had also shown a correlation with clinical outcome in melanoma patients during treatment with anti-CTLA-4 blockade." (PMID 32117298, 2020). "Such developments led to the first US FDA-approved immune checkpoint inhibitor (ICI), ipilimumab—a cytotoxic T-lymphocyte antigen-4 (CTLA-4)-targeting monoclonal Ab—for the treatment of patients with advanced melanoma." (PMID 33207653, 2020). "Recent studies addressed the question of the impact of tumor infiltration by B cells and presence of TLS on patient survival and response to PD-1 blockade in soft-tissue sarcoma and to PD-1 and CTLA-4 blockade in melanoma." (PMID 32457745, 2020). "Clinical trials in melanoma brain metastases with combined PD-1/CTLA-4 blockade showed ~50% intracranial response rate 27,28." (PMID 32194848, 2020).
melanoma (continued). "For example, STING-deficient mice treated with anti-CTLA4 and anti-PDL1 mAbs showed poorer B16 melanoma tumor control than WT mice." (PMID 32774773, 2020). "Melanoma patients showing high PD-L1 expression in the tumor, when treated with ionizing radiation together with anti-CTLA4, developed T cells with an exhausted phenotype and the tumors progressed." (PMID 32365838, 2020). "After approval of the first PD-1/PD-L1 and CTLA-4 blocking antibodies for melanoma, checkpoint inhibitors are under intense investigation in many tumor entities." (PMID 32899197, 2020). "Most prominently, melanoma patients bearing liver metastasis have reduced CTLA-4 and PD-1 co-expression in CD8+ T cells, which has been shown to stratify therapeutic response to immune checkpoint inhibitor treatment." (PMID 32849557, 2020). "Concurrent combination of nivolumab targeting PD-1 and ipilimumab targeting CTLA-4 was reported to regress advanced melanoma by 80%." (PMID 33076303, 2020). "One patient was treated with cyclosporine due to liver transplantation and another patient received ipilimumab, an antibody targeting cytotoxic T-lymphocyte-associated protein 4 (CTLA-4), to treat melanoma." (PMID 31950335, 2020). "The “viral defense” gene expression signature associated with HERVs expression is also predictive of immune checkpoint responses in melanoma patients, and DNMTis treatment sensitize to anti-CTLA-4 therapy in a mouse melanoma model." (PMID 32155827, 2020). "Cross-validation cohorts to estimate the accuracy of the predictive models showed CCRs of 83% for anti-CTLA-4 and 78% or 68% for anti-PD-1 in melanoma or NSCLC, respectively." (PMID 33427690, 2020). "Of note, while radiation therapy-induced immunogenic cell death occurs within 1–3 days in breast tumor cells, anti-tumor immunity to melanoma is improved when anti-CTLA-4 antibody precedes radiation therapy." (PMID 32873251, 2020). "Ipilimumab, accepted by the FDA in 2011 for the treatment of melanoma, blocks inhibitory signaling based on CTLA-4 and, thus, increases the activation and expansion of cytotoxic T cells." (PMID 33171792, 2020). "IL-2-based compounds in combination with CTLA-4 blockade should be studied in advanced melanoma patients who fail to benefit from first-line PD-1 blockade." (PMID 31998643, 2020). "Radiation with dual checkpoint blockade reportedly induces optimal responses in melanoma, with a previous preclinical study of melanoma demonstrating that anti-CTLA-4 increases the CTL:Treg ratio while anti-PD-L1 rescues T cell exhaustion." (PMID 32218257, 2020). "Multiple phase II and III studies have shown that ipilimumab and nivolumab are active in advanced melanoma and that the combination therapies involving PD-1 or CTLA-4 inhibitors presented a superior efficacy when compared to the individual monotherapies." (PMID 32117271, 2020). "Other novel anti-CTLA-4 agents in early stage clinical trials in solid tumors, including melanoma, are AGEN1884, ADU-1604 and MK1308." (PMID 32503946, 2020). "Delay in tumor growth and survival prolongation were witnessed in melanoma with a combination of CTLA-4 blockade and IL-2 immunotherapy, indicating synergism." (PMID 32117298, 2020). "Examples include EGFR and ALK inhibitors in non-small cell lung cancer, BRAF inhibitors in melanoma, HER2-targeting agents in breast cancer, and immune checkpoint inhibitors of CTLA4 or PDL1 in melanoma or non-small cell lung cancer 6-10." (PMID 31903155, 2020). "Taken together, frequencies of circulating mo-MDSCs have a prognostic and predictive potential in melanoma therapy with anti-CTLA-4." (PMID 32992737, 2020). "In human melanomas, over-expression of MAGE-A, a cancer-germline antigen, is associated with CTLA-4 blockade resistance and can downregulate autophagy, suggesting autophagy induction as a potential therapeutic approach to improve CTLA-4 inhibitors efficacy." (PMID 33324568, 2020).